ELAVL1 (ELAV like RNA binding protein 1)
Diseases named in the same sentence as ELAVL1 in open-access papers (continued):
Sharing a sentence is not in itself a finding about the gene and the disease.
Salmonella Infections (3 papers, 2013 to 2025). Infections with bacteria of the genus SALMONELLA. "Additionally, in this study, the ELAVL1 gene was found to be enriched in pathways such as human immunodeficiency virus type 1 infection, Epstein-Barr virus infection pathway, human papillomavirus infection, measles, and Salmonella infection." (PMID 38714976, 2024).
ZIKV infection (3 papers, 2019 to 2023). "We recently showed that during ZIKV infection, HuR (or ELAVL1) is re-localized from the nucleus to ZIKV replication sites." (PMID 32380717, 2020).
abnormal vision (2 papers, 2016 to 2020). "Human antigen R (HuR or ELAVL1) is a member of the embryonic lethal abnormal vision (ELAV) family of RNA‐binding proteins." (PMID 33391635, 2020). "A key factor that mediates ARE-mRNA stability is HuR (ELAVL1), which is a member of a family of proteins analogous to the Drosophila embryonic-lethal abnormal vision (ELAV) proteins." (PMID 27677075, 2016).
allergic asthma (2 papers, 2022 to 2026). A asthma with a basis in a pathological type I hypersensitivity reaction. "We investigated whether the RNA-binding protein HuR (ELAVL1) functions as a post-transcriptional regulator of GATA3-driven type 2 inflammation in allergic asthma." (PMID 42094570, 2026).
bladder tumors (2 papers, 2021 to 2024). "For instance, YBX1 was found to recruit ELAV-like RNA-binding protein 1 (ELAVL1) and improve the stability of target mRNAs in bladder tumors." (PMID 39117671, 2024).
chronic lung disease (2 papers, 2021). According to the definitions of the American and British Thoracic Societies, including pulmonary functional tests, X-rays, and CT scans for items such as fibrosis, bronchiectasis, bullae, emphysema, nodular or lymphomatous abnormalities. "Additionally, the combined role of APP and ELAVL-1 in chronic lung diseases and their effect on different macrophage subtypes are not known." (PMID 33478018, 2021).
colon adenoma (2 papers, 2013 to 2015). An adenoma that arises from the colon. "ELAVL1/HuR is enriched in the nuclear matrix fraction and linked to the regulation of colon adenoma to carcinoma progression." (PMID 26442106, 2015).
coronary artery disease (2 papers, 2024). "We identified eight hub genes (CIRBP, USP7, ELAVL1, ATG13, ALOXE3, PRKAA2, USP11, SLC38A1) that exhibited significant differences between coronary heart disease (CAD) patients and healthy controls." (PMID 39610972, 2024).
Huntington disease (2 papers, 2022). Huntington disease (HD) is a rare neurodegenerative disorder of the central nervous system characterized by unwanted choreatic movements, behavioral and psychiatric disturbances and dementia. "In Huntington’s disease, which is caused by mutations in the HTT gene and abnormal accumulation of the HTT protein, the HTT protein itself induces ELAVL1 to stabilize HTT mRNA, forming a positive feedback loop." (PMID 35465324, 2022).
pancreatitis (2 papers, 2020 to 2025). Inflammation of the pancreas. "In terms of pancreatitis, we also knew that ELAVL1 was associated with pancreatitis‐like inflammatory microenvironment." (PMID 39588852, 2025). "In conclusion, ELAVL1‐dependent SOAT2 exacerbated pancreatic exocrine cell injury by inactivating the NRF2/HO‐1 pathway in pancreatitis." (PMID 39588852, 2025).
sarcopenia (2 papers, 2021 to 2025). Progressive decline in muscle mass due to aging which results in decreased functional capacity of muscles. "In our study, ELAVL1 was elevated in the sarcopenia group compared to frailty syndrome and geriatric control groups." (PMID 40034697, 2025). "Furthermore, we observed increased expression of SIRT3, SIRT6, FOXO1, and ELAVL1 in patients with sarcopenia compared to the geriatric controls and the frailty group, although these differencesdid not reach statistical significance." (PMID 40034697, 2025). "The hypothesis is that genes involved in epigenetic modifications, such as SIRT1, SIRT3, SIRT6, FOXO1, FOXO3A, DNMT3A, and ELAVL1, are critical for the development of sarcopenia and could be used as biomarkers for the diagnosis and monitoring of the disease." (PMID 40034697, 2025).
acute pancreatitis (1 paper, 2025). An acute inflammatory process that leads to necrosis of the pancreatic parenchyma. "Therefore, we constructed the ELAVL1/SOAT2/NRF2/HO‐1 axis to elucidate the mechanism underlying SOAT2's regulation in the progression of acute pancreatitis, with the goal of identifying potential therapeutic targets for this disorder." (PMID 39588852, 2025). "Taken together, ELAVL1‐dependent SOAT2 aggravated pancreatic exocrine cell injury by inactivating the NRF2/HO‐1 pathway in acute pancreatitis." (PMID 39588852, 2025).
age-related macular degeneration (1 paper, 2025). Age-related loss of vision in the central portion of the retina (macula), secondary to retinal degeneration. "In age-related macular degeneration (AMD), Elavl1 worsens retinal pigment epithelial cell dysfunction, leading to drusen formation." (PMID 40000387, 2025).
Anxiety (1 paper, 2024). Intense feelings of nervousness, tension, or panic often arise in response to interpersonal stresses. "The results of this study confirm the association between ELAVL1 expression and comorbid anxiety in MDD patients." (PMID 38714976, 2024). "ELAVL1 was associated with comorbid anxiety in MDD patients." (PMID 38714976, 2024). "Among all the m6A genes, ELAVL1 and YTHDC2 are closely associated with MDD, ELAVL1 is related to comorbid anxiety in MDD." (PMID 38714976, 2024).
Arrhythmia (1 paper, 2018). Any cardiac rhythm other than the normal sinus rhythm. "Some studies attempted to regulate the expression of SCN5A mRNA through exogenous ingestion of the messenger RNA (mRNA) stabilizing protein ELAVL1/HuR and to verify whether it was beneficial to control arrhythmia." (PMID 30364184, 2018).
cardiomyopathy (1 paper, 2020). A disease of the heart muscle or myocardium proper. "We have shown previously that loss of Hu antigen R (HuR; encoded by ELAVL1) can destabilize SCN5A and contribute to arrhythmic risk in cardiomyopathy." (PMID 33108349, 2020).
cervical squamous cell carcinoma (1 paper, 2024). A squamous cell carcinoma arising from the cervical epithelium. "ELAVL1 was overexpressed in many tumors, including kidney chromophore, rectum and colon adenocarcinomas, lung and cervical squamous cell carcinomas, and breast cancer carcinoma, confirming previous data from the literature." (PMID 38965208, 2024).
dementia (1 paper, 2020). Loss of intellectual abilities interfering with an individual's social and occupational functions. "EGFR has been linked to dementia, while mice with neuron-specific deletion of ELAVL1 have been reported to have a phenotype resembling motor neuron disease." (PMID 32327964, 2020).
depression (1 paper, 2024). "Previous research has shown that ELAVL1 is involved in the PI3K-PDK1 pathway, which is associated with depression, suggesting that one of the mechanisms by which ELAVL1 is related to MDD is through cellular signal transduction pathways." (PMID 38714976, 2024).
dermatomyositis (1 paper, 2025). Dermatomyositis (DM) is a type of idiopathic inflammatory myopathy characterized by evocative skin lesions and symmetrical proximal muscle weakness. "Intriguingly, pharmacologic inhibition of ELAVL1 potently reduced the constitutive secretion of pro-inflammatory cytokines in skin fibroblasts from patients with type I interferonopathies and dermatomyositis, providing a new approach to treat RIG-I/cGAS-dependent interferonopathies." (PMID 39707025, 2025).
disc degeneration (1 paper, 2020). "The qPCR results showed that ELAVL1(HuR) expression was decreased as the disc degeneration grade rises." (PMID 33330514, 2020).
endometriosis (1 paper, 2017). The growth of functional endometrial tissue in anatomic sites outside the uterine body. "In order to examine if HuR/TTP axis contributes to the pathophysiology of endometriosis, we evaluated expression of Zfp36, Zfp36l1, Zfp36l2 and Elavl1 in eutopic and ectopic lesions obtained from syngeneic BALB/cByJ mouse model of endometriosis." (PMID 28724967, 2017).
esophageal tumor (1 paper, 2020). "The results further confirmed that angustoline suppressed esophageal tumors through regulating LKB1/AMPK/ELAVL1/LPCAT2 and consequently inhibiting the excessive conversion from LPC (16:0) to PC (16:0/18:1)." (PMID 32733803, 2020). "Additionally, KYSE450 tumor bearing mouse model was constructed, the role of angustoline in inhibiting esophageal tumors through regulating LKB1/AMPK/ELAVL1/LPCAT2 pathway was validated, and found that the conversion from LPC (16:0) to PC (16:0/18:1) was blocked by angustoline in some degree." (PMID 32733803, 2020). "Therefore, LKB1, AMPK, ELAVL1, and LPCAT2 were chosen as the possible candidate factor in esophageal tumor models in our study, their roles in the growth and development of esophageal tumor, as well as the effect of angustoline on their expression levels, were investigated." (PMID 32733803, 2020). "Considering the study on the effects of angustoline on esophageal tumor was rarely reported, the present manuscript investigated anti-tumor role of angustoline in vitro and in vivo, and explored the regulation of angustoline in LKB1/AMPK/ELAVL1/LPCAT2 pathway and phospholipid remodeling." (PMID 32733803, 2020).
folate deficiency (1 paper, 2017). A nutritional condition produced by a deficiency of FOLIC ACID in the diet. "Previous studies demonstrated that folate deficiency affected the gene expression of Esr1, Cav1, and Elavl1." (PMID 28445960, 2017). "To investigate the effect of folate deficiency on the methylation status of the ESR1, CAV1 and ELAVL1 promoters, we selected 20 semen samples with low ( < 25th percentile) and high (> 75th percentile) folate concentrations." (PMID 28445960, 2017). "In addition, folate deficiency can evidently reduce the gene expression levels of ESR1, CAV1 and ELAVL1, which are critical to spermatogenesis." (PMID 28445960, 2017).
influenza (1 paper, 2024). An acute viral infection of the respiratory tract, occurring in isolated cases, in epidemics, or in pandemics; it is caused by serologically different strains of viruses (influenzaviruses) designated A, B, and C, has a 3-day incubation period, and usually lasts for 3 to 10 days. "Similarly, hsa-miR-5003-3p, EP300, Valproic Acid, Influenza, and ELAVL1 have interactive relationships centered around EIF2AK2, while hsa-miR-6893-3p, EP300, Calcitriol, Influenza, and HNRNPA2B1 exhibit interactive relationships centered around OASL." (PMID 38601162, 2024).
invasive ductal carcinomas (1 paper, 2024). "Coherently, ELAVL1 is more expressed in more aggressive BRCA subtypes, such as the triple negative one, the PAM50 basal subtype, and the invasive ductal carcinomas." (PMID 38965208, 2024).
juvenile astrocytoma (1 paper, 2021). "Embryonic Lethal, Abnormal Vision, Drosophila (ELAVL-1 or Human antigen R (HuR)) is an RNA-binding protein associated with juvenile astrocytoma and pancreas adenocarcinoma." (PMID 33478018, 2021).
male infertile (1 paper, 2019). "Mice null for ELAVL1 are male infertile while none of the others has been studied in vivo." (PMID 31541158, 2019).
pancreatic disorders (1 paper, 2025). "ELAVL1 is a highly conserved family of RBPs that has been implicated in various diseases, including pancreatic disorders." (PMID 39588852, 2025).
Parkinson disease (1 paper, 2024). A progressive degenerative disorder of the central nervous system characterized by loss of dopamine producing neurons in the substantia nigra and the presence of Lewy bodies in the substantia nigra and locus coeruleus. "Previous studies have found that ELAVL1 is involved in the pathogenesis of Parkinson’s disease, indicating the involvement of the ELAVL1 gene in the biological mechanism of neurodegeneration in MDD patients during m6A methylation." (PMID 38714976, 2024).
polycystic ovary syndrome (1 paper, 2017). A disorder that manifests as multiple cysts on the ovaries. "When used to a study a plasma lipidome dataset of polycystic ovary syndrome, 14 enzymes were identified, of which 3 are linked to ELAVL1—an mRNA stabiliser." (PMID 28596719, 2017).
rectal tumor (1 paper, 2019). "Except for ELAVL1, all of the other six hub genes were significantly downregulated in colon and rectal tumor tissues compared to those in controls." (PMID 31934534, 2019).
retinal hemangioblastoma (1 paper, 2019). A hemangioblastoma that arises from the retina.
rheumatic disease (1 paper, 2025). "The development of rheumatic disease was associated with a lower level of DNMT3A in the frailty patients group (p=0.002).Furthermore, in this group, a correlation between appendicular skeletal muscle mass (ASMM) and the expression of ELAVL1 (r=0.59, p=0.026) was observed." (PMID 40034697, 2025).
synovial sarcoma (1 paper, 2024). "Among them, METTL3, YTHDC1, YTHDC2, RBMX, and ELAVL1 were significantly upregulated in synovial sarcoma tissue." (PMID 38549939, 2024).
Vision (1 paper, 2020). "Peptides that specifically bound to biotin-labeled MAARS transcript were identified by liquid chromatography-mass spectrometry (LC-MS/MS) analysis, capturing HuR (Hu antigen R, also known as ELAVL1, Embryonic Lethal, Abnormal Vision, Drosophila-Like 1) as a MAARS-binding protein." (PMID 33262333, 2020).
cancer (359 papers, 2006 to 2026). A tumor composed of atypical neoplastic, often pleomorphic cells that invade other tissues. "ELAVL1 is closely linked to the development and progression of various inflammatory diseases, metabolic disorders, and cancers." (PMID 40958880, 2025). "MUC2 has been reported to be associated with cancer metastatic processes, and ELAVL1 was identified as a central oncogenic driver for malignant growth and metastasis of peripheral nerve sheath tumor." (PMID 39593114, 2024). "ELAVL1 has been identified as an oncogenic gene in various cancers, and its expression is closely associated with the progression of cancer." (PMID 36513874, 2023). "ELAVL1/HuR is an RNA-binding protein that has been shown to be an important post-transcriptional regulator of many cancer-associated pro-survival genes such as VEGF, WEE1, and IDH1." (PMID 36552005, 2022). "Previous studies have demonstrated that higher ELAVL1 expression is closely associated with unfavorable prognosis in various cancer types." (PMID 35887229, 2022). "Overexpression of APP and TRIM25 in cancer patients was associated with low overall survival and the reverse was true for ELAVL1." (PMID 34193143, 2021). "ELAVL1 has been reported as an oncogene in many cancers and closely associated with tumor progression." (PMID 32370736, 2020). "ELAV-like RNA binding protein 1 (HuR), an RNA-binding posttranscriptional regulator, affects mRNA stability through binding to the RNA motif and is implicated in cancer formation, progression, and metastasis." (PMID 32429086, 2020). "OCC1 enhances the binding of an ubiquitin E3 ligase to ELAVL1 and renders the RBP susceptible to ubiquitination and degradation, thereby reducing the levels of ELAVL1 and, in turn, of its target mRNAs, including the mRNAs associated with cancer cell growth." (PMID 32957640, 2020). "LncRNA ZEB1-AS1 binds to ELAVL1 (HuR), a cancer-associated RBP protein, to stabilize Zinc Finger E-Box Binding Homeobox 1(ZEB1) mRNA." (PMID 33050646, 2020). "For example, in module 1, ELAVL1 has been implicated in a variety of biological processes and has been linked to a number of diseases, including cancer." (PMID 31417727, 2019). "Human antigen R (HuR, encoded by the ELAVL1 gene) is a ubiquitously expressed RBP whose role in cancer has become increasingly evident in recent years." (PMID 26314962, 2015). "Consequently, ELAVL1 has been implicated in several cellular processes ranging from development to angiogenesis and has also been linked to inflammatory diseases and cancer." (PMID 39707025, 2025). "Elevated ELAVL1 (hereon will be referred to as HuR) expression has been observed in several cancers and regulates the stability of many cancer-associated transcripts during cancer progression and metastasis." (PMID 36918912, 2023). "The messenger ELAVL1 is a cancer-associated RNA-binding protein, also known as human antigen R. It is a ubiquitous member of the RBP family and acts as a positive regulator of RNA stability by stabilizing the 3 ́-untranslated region of the AU-rich cis-acting element (Ares) of the mRNA." (PMID 36324584, 2022). "ELAVL1 has been implicated in a variety of biological processes, and it is highly expressed in many cancers and could be potentially useful in cancer diagnosis, prognosis, and therapy." (PMID 35722625, 2022). "Given the reportedly oncogenic potential of the ELAVL1 protein in various types of cancer, we speculated that the OSCC-associated upregulation of circFLNB could be partly attributed to this RBP." (PMID 32785098, 2020). "ELAVL1 enhances pathogenic gene expression necessary for cancer development." (PMID 31440515, 2019). "However, dysregulation of ELAVL1 has been implicated in various diseases, including cancer." (PMID 39390359, 2024).